INS (insulin)
Diseases named in the same sentence as INS in open-access papers (continued):
Sharing a sentence is not in itself a finding about the gene and the disease.
type 1 diabetes (continued). "Type 1 diabetes (T1D) is an autoimmune condition where the body’s immune cells destroy their insulin-producing pancreatic beta cells leading to dysregulated glycaemia." (PMID 33153010, 2020). "Using national 2018 claims data, we estimated out-of-pocket spending for insulin and other health care services for privately insured patients with type 1 diabetes." (PMID 32478819, 2020). "In people with type 1 diabetes, the rate of hypoglycaemia was similar between those who were only prescribed i.v.-administered insulin and those who were only administered a combination of rapid- and long-acting insulin analogue." (PMID 32300821, 2020). "Type 1 diabetes (T1D) is an autoimmune disease resulting from the destruction of insulin-producing β-cells in the pancreas which is promoted by T-cells, producing autoantibodies." (PMID 33425976, 2020). "The mainstay of treatment of type 1 diabetes is lifestyle modification, which includes a change in diet and increased physical activity along with insulin replacement." (PMID 33005503, 2020). "Type 1 diabetes remains a major threat to patients, as a specific cure is currently elusive and present treatment requires continuous glucose monitoring and strict insulin therapy." (PMID 32549343, 2020). "For this purpose, we focused on the AD type 1 diabetes (T1D) which arises through immune destruction of insulin-producing β-cells in the pancreas." (PMID 32184781, 2020). "Of note, PTPRN2 has been shown to be a target of autoantibodies in Type I diabetics and a regulator of insulin secretion." (PMID 32291385, 2020). "Partial clinical remission (PCR) is a transitory period characterized by the residual endogenous insulin secretion following type 1 diabetes (T1D) diagnosis and introducing the insulin therapy." (PMID 32635304, 2020). "Type 1 diabetes (T1D) are characterized by a targeted autoimmune destruction of the insulin‐producing β‐cells in the pancreatic islets of Langerhans and the ensuing insufficient insulin production." (PMID 32935914, 2020). "Continuous Subcutaneous Insulin Infusion (CSII) was introduced as a mode of insulin administration for type 1 diabetes in the late 1970s." (PMID 32576284, 2020). "Type 1 diabetes (T1D) is the consequence of immune-mediated destruction of the insulin-producing pancreatic β-cells." (PMID 32967650, 2020). "Type 1 diabetes is an autoimmune disease typically starting in childhood that culminates in the destruction of insulin‐producing beta cells in the pancreas." (PMID 32697399, 2020). "Type 1 diabetes occurs after an immune-mediated destruction of pancreatic beta cells, which in the end leads to lifelong dependence on insulin treatment." (PMID 32119659, 2020). "On the other hand, people with Type 1 Diabetes cannot produce insulin endogenously at all and hence must receive external insulin regularly." (PMID 32155149, 2020). "It was possible to distinguish diabetes type 1 and type 2 by joining two pieces of information present on the baseline: age at diagnosis and the use of insulin as the first option for treatment." (PMID 32120955, 2020). "Effectiveness and compliance of medication for enhancing immune response in patients with systemic disease (GCF in cyclical neutropenia or insulin treatment in insulin-dependent diabetes) is ascertained by regular monitoring of gingival and periodontal health." (PMID 32864126, 2020). "Insulin and other insulin granule cargoes are also major targets of autoimmunity in type 1 diabetes." (PMID 32894308, 2020). "Type 1 diabetes (T1D) results from auto-reactive killing of the pancreatic islet insulin-producing β-cells." (PMID 32411136, 2020). "Earlier studies provided evidence that human and mouse beta EV contain major auto-antigens of type 1 diabetes such as GAD65, islet-associated antigen 2, Znt8, and insulin." (PMID 33101266, 2020). "The current standard treatment for Type 1 diabetes is the administration of exogenous insulin to manage blood glucose levels." (PMID 33282827, 2020).
type 1 diabetes (continued). "For example, if a patient has type 1 diabetes at a young age, then the parents of the patient should be educated about diet plans, hypoglycemia, and giving insulin." (PMID 33352875, 2020). "The pancreas of patients with type 1 diabetes is unable to produce insulin and they will therefore usually have a decreased level of C‐peptide." (PMID 32142224, 2020). "Intensive insulin treatment for type-I diabetes involves multiple daily subcutaneous insulin injections (3 to 5 per day), with both long-acting basal insulin and short-acting prandial insulin." (PMID 32785196, 2020). "The typical treatment of type 1 diabetes involves insulin therapy, however, tight glycemic control is very important to prevent microvascular and macrovascular complications." (PMID 33005503, 2020). "In an insulin delivery study for type 1 diabetes, hollow MNs provided faster absorption through faster onset and offset compared with SC." (PMID 33228098, 2020). "Type 1 diabetes occurs when the immune system in the body attacks and destroys the pancreatic cells that produce insulin." (PMID 33066521, 2020). "Type 1 diabetes (T1D) is generally viewed as a Th1-mediated autoimmune disease in which cytotoxic T lymphocytes attack insulin-producing beta cells in pancreatic islets." (PMID 32346380, 2020). "An insulin replacement therapy, most commonly the administration of recombinant human insulin, is used to treat type I diabetes." (PMID 33209247, 2020). "Studies demonstrated that inhaled insulin controlled blood glucose (HbA1c) with comparable results to subcutaneous insulin in 6 children with type-I diabetes." (PMID 32785196, 2020). "We then compared insulin release (measured as C‐peptide) at different blood glucose concentrations in patients newly diagnosed for type 1 diabetes (having residual insulin production) to healthy individuals." (PMID 32618430, 2020). "We first examined effector T cell trafficking to the pancreatic islets in the RIP-mOVA inducible model of type 1 diabetes, in which membrane bound Ovalbumin (mOVA) is expressed in beta cells under the rat insulin promoter (RIP)." (PMID 32510333, 2020). "Disease is associated with impaired glucose metabolism and after 20 years of type-1 diabetes, 80% of patients with insulin treated type-1 diabetes and 50% of patients with type-2 diabetes will have some degree of DR." (PMID 33584278, 2020). "Type 1 diabetes (T1DM) is a chronic autoimmune disease, with a strong genetic background, leading to a gradual loss of pancreatic beta-cells, which secrete insulin and control glucose homeostasis." (PMID 32759843, 2020). "In patients with type-I diabetes, inhaled insulin should be taken with subcutaneous long-acting insulin." (PMID 32785196, 2020). "The data set consists of high-precision self-recorded data collected from three real subjects with type 1 diabetes incorporating blood glucose, insulin, diet, and events of infection." (PMID 32784179, 2020). "She had been clinically diagnosed with type 1 diabetes 1 month prior, and administered 14 units of insulin glargine 300 U/mL per day." (PMID 32871938, 2020). "In this study, several models based on this methodology have been developed to calculate the basal insulin dose in patients with type I diabetes using subcutaneous insulin infusion pumps." (PMID 33204261, 2020). "Type 1 diabetes (T1D) is a chronic immune mediated disease in which insulin-producing β cells are destroyed leading to lifelong insulin deficiency." (PMID 33679609, 2020). "Although detectable C-peptide secretion is common, for those diagnosed in childhood, however, our results do not support the assertion that “the majority of patients with long-duration Type 1 diabetes are insulin microsecretors”." (PMID 31438962, 2019). "‘‘Because I live with type 1 diabetes I have to do a complete insulin replacement, which involves balancing for activity, ambient temperature, stress levels, insulin sensitivity of my body." (PMID 31166971, 2019).
type 1 diabetes (continued). "The present study was conducted in order to develop the Insulin Treatment Self-management Scale: Child Form and Parent Form for children of ages 8-18 with type 1 diabetes." (PMID 30905141, 2019). "Type 1 diabetes (T1D) is a chronic multi-factorial disorder characterized by the immune-mediated destruction of insulin-producing pancreatic beta cells." (PMID 31199784, 2019). "Development of a methodologically designed scale was conducted to investigate insulin treatment self-management of children with type 1 diabetes." (PMID 30905141, 2019). "In type 1 diabetes mellitus (T1DM) and insulin-deficient animals, serum ANGPTL8 levels were increased." (PMID 31346314, 2019). "Type 1 diabetes mellitus (T1DM) is a chronic multifactorial disease that is considered to be caused by selective autoimmune destruction of the pancreatic beta-cells which makes the affected individual dependent on exogenous insulin." (PMID 30845908, 2019). "AL selectively inhibits glucokinase, the glucose sensor of beta cell and inhibits glucose-stimulated insulin secretion that leads to a state of insulin-dependent diabetes (type 1 DM) by its ability to induce ROS formation." (PMID 31823816, 2019). "This methodologically designed scale was created to identify insulin treatment self-management for children with type 1 diabetes." (PMID 30905141, 2019). "While the efficacy of MSC-differentiated insulin-producing cells in type 1 diabetes is relatively well established, the therapeutic effects of undifferentiated MSCs in T2DM are only now being evaluated." (PMID 31018536, 2019). "A study carrying out cortisone acetate test in young type 1 diabetes subjects reported decreased 11βHSD 1 activity and inverse correlation was found with insulin dose requirement." (PMID 30678666, 2019). "In type 1 diabetes (T1D), the sophisticated mechanisms regulating glucose homeostasis are degraded because of the autoimmune destruction of insulin-producing pancreatic β-cells, which renders internal insulin secretion practically absent." (PMID 31817678, 2019). "The abundance of circulating insulin gene promotor cell-free DNA (INS cfDNA) was shown to be valuable as a predictive biomarker of β-cell death in individuals with Type 1 diabetes (T1D) as well as with gestational diabetes." (PMID 30953560, 2019). "Type 1 diabetes is a chronic autoimmune disorder that results from the tissue specific destruction of insulin producing beta-cells within pancreatic islets." (PMID 30906293, 2019). "Individuals with type 1 diabetes (T1D) experience auto-immune-mediated destruction of insulin-producing β-cells and consequently require life-long insulin therapy." (PMID 31243300, 2019). "Type 1 diabetes (T1D) is a multifactorial, organ/cell-specific disease resulting from an autoimmune destruction of insulin-producing β cells of the endocrine pancreas by CD4+ and CD8+ T cells, as well as macrophages infiltrating the islets." (PMID 31139178, 2019). "In people with type 1 diabetes using intensive insulin therapy 75 g or more of protein alone significantly increases postprandial glycemia from 3 to 5 h in people with type 1 diabetes." (PMID 30871141, 2019). "We aimed to assess the clinical impact of preserved endogenous insulin secretion, measured using C‐peptide, in people with long duration Type 1 diabetes." (PMID 30955221, 2019). "John’s son Rob was diagnosed with type 1 diabetes at age 3 and wore a traditional tubed insulin pump." (PMID 30239214, 2019). "Type 1 diabetes (T1D) is a T-cell–mediated autoimmune disease that destroys insulin-producing pancreatic β-cells." (PMID 31547302, 2019). "We will assess effectiveness of 6-month day-and-night closed-loop insulin delivery compared with usual care (conventional or sensor-augmented pump therapy) in children and adolescents with type 1 diabetes." (PMID 31164368, 2019).
type 1 diabetes (continued). "Type 1 diabetes (T1D) is a complex autoimmune disease resulting from specific immunological destruction of pancreatic insulin-producing beta cells, leading to hyperglycemia, and ketoacidosis." (PMID 31787971, 2019). "Further, we evaluated if testing with this novel platform enables earlier detection of insulin autoantibodies in individuals that have first-degree relatives with type-1 diabetes than currently used approaches." (PMID 30730939, 2019). "Insulin soluble for type 1 diabetes, was the most expensive of all the NCD medicines across all sectors requiring 15.6 days, 8.1 days and 9.9 days of work to afford in retail pharmacies, CHAM and private clinics respectively." (PMID 30753219, 2019). "There is also evidence that protein and fat counting is advantageous in children and adolescents with type 1 diabetes treated with insulin pumps." (PMID 30871141, 2019). "Thereafter, these children were classified as having insulin-dependent diabetes, which was later re-termed as type 1 diabetes with a dependence on insulin to survive." (PMID 31558146, 2019). "This study was a valid and reliable scale for measuring insulin treatment self-management in children with type 1 diabetes." (PMID 30905141, 2019). "We report a case of a 14-year-old boy who had type 1 diabetes for 4 years treated with insulin therapy, also having adrenal insufficiency treated with hydrocortisone who presented with ketoacidosis and excruciating abdominal pain." (PMID 30723557, 2019). "In type I diabetes (T1D), insulin-producing pancreatic β cells are impaired and/or lost through immune-mediated mechanisms." (PMID 30899071, 2019). "In our laboratory, we have previously shown that 60 mg/kg of STZ selectively destroys pancreatic beta cells that secrete insulin, thereby producing a hyperglycaemic type 1 diabetic animal model." (PMID 31828165, 2019). "Type 1 diabetes was defined by rapid insulin requirement (within 3 years of diagnosis) and severe endogenous insulin deficiency (C-peptide <200 pmol/L)." (PMID 31558459, 2019). "This specific app is designed for people with type 1 diabetes and knowing the amount of carbohydrates in meals is essential for adjusting insulin dosage." (PMID 31452522, 2019). "Incidence rates of type 1 diabetes for ages 0–19 years in the United States (n = 59,932,523 children and adolescents with two type 1 diabetes diagnosis codes with the use of insulin) were graphed, with stratification by age group." (PMID 31197227, 2019). "For example, in cell replacement therapies for type 1 diabetes (T1D), transplanted insulin producing cells rely on nearby vasculature to survive and function." (PMID 31601796, 2019). "Type 1 diabetes (T1D) is characterized by hyperglycemia resulting from autoimmune destruction of insulin-secreting pancreatic β-islet cells." (PMID 30171596, 2019). "In this study, we describe novel anti-insulin B cell populations that reside in the pancreatic islets during type 1 diabetes development." (PMID 31444529, 2019). "In this study, we aimed to develop an AuNC-based glucose-responsive insulin-releasing system for glucose control in type 1 diabetes." (PMID 31159842, 2019). "The limitation of achieving optimal glycaemic control with intensive treatment in Type 1 diabetes is usually hypoglycaemia, which prevents up‐titration of insulin doses." (PMID 30955221, 2019). "The aim of the study was to develop an Insulin Treatment Self-management Scale; both Child Form and Parent Form for children ages 8-18 with type 1 diabetes." (PMID 30905141, 2019). "The need for insulin was significantly greater for patients with acute‐onset type 1 diabetes than those with slowly progressive type 1 diabetes." (PMID 30919585, 2019). "The present study will assess the efficacy, safety, utility and acceptability of 6-month day-and-night hybrid closed-loop insulin delivery during unrestricted living in comparison to usual care in children and adolescents with type 1 diabetes." (PMID 31164368, 2019).
type 1 diabetes (continued). "Summing up, the improvement in the postprandial plasma glucose control in people with type 1 diabetes depends primarily on properly adjusting the insulin dose to the meal being consumed." (PMID 30871141, 2019). "Two phase 3 trials and a meta-analysis involving patients with type 1 diabetes have demonstrated lower rates of nocturnal hypoglycaemia with insulin degludec compared to insulin glargine U100." (PMID 31337371, 2019). "Insulin was discovered as a life-saving drug for the treatment of type 1 diabetes and has also had a profound impact on the treatment of T2D." (PMID 31031702, 2019). "Mean glucose levels, carbohydrate intake, and adjustment of basal insulin in individuals with type 1 diabetes during a 90 km cross-country skiing race (Vasaloppet) and the duration of the physical activity (A–J)." (PMID 31496994, 2019). "Type 1 Diabetes results from autoimmune destruction of insulin‐producing beta cells of the pancreas; therefore, insulin must be supplied in an alternative way." (PMID 30918692, 2019). "First, this study involved the use of crucial factors including alcohol usage, physical activity, BMI, and HbA1c level for finding the best insulin dosage for patients with type 1 diabetes." (PMID 31464196, 2019). "Overnight insulin withdrawal in patients with type 1 diabetes increases basal (resting) energy expenditure, a response that has been attributed to hyperglucagonemia and is associated with increased protein catabolism." (PMID 31815933, 2019). "There do not yet exist, as far as we know, in the literature any tools to measure insulin treatment self-management levels of children with type 1 diabetes." (PMID 30905141, 2019). "We successfully developed a phenylboronic acid-functionalized gold nanocluster system (AuNC-PBA-Ins) for responsive insulin release and glucose regulation in type 1 diabetes." (PMID 31159842, 2019). "With respect to the glycemic lowering efficacy, there was no major difference, as shown in a previous study, in 30 prepubertal children with type 1 diabetes using insulin glargine as their basal insulin." (PMID 31886089, 2019). "Due to its inherent flexibility of insulin dose adjustment, the predominant mode of delivery in patients with type 1 diabetes is via a subcutaneous insulin pump, also known as continuous subcutaneous insulin infusion." (PMID 31261760, 2019). "Frequent blood glucose (BG) checks and multiple daily insulin injections have become standard of care in Type 1 diabetes (T1DM) management." (PMID 30875898, 2019). "The risk allele (T‐allele) frequency of BACH2 rs3757247 in the six patients with insulin‐triggered type 1 diabetes was 0.75, and was significantly more frequent than that in 86 control Japanese participants (0.43; P = 0.0382)." (PMID 30970177, 2019). "Type 1 diabetes (T1D) is an organ specific autoimmune disease that results from the destruction of insulin producing β-cells in the pancreatic islets." (PMID 31653894, 2019). "Type 1 diabetes is also a T lymphocyte driven disease which results in the destruction of insulin producing pancreatic islet cells." (PMID 30978214, 2019). "This study explores the influence of socioeconomic factors in gaining access to intensive insulin regimens for adults with type 1 diabetes." (PMID 31604437, 2019). "In 1922 the pancreatic insulin was successfully purified and applied for Leonard Thompson, a 14 years old boy suffering type 1 diabetes, which ushered in the era of protein therapeutics." (PMID 31119124, 2019). "In this study, we aim to develop a glucose-responsive insulin-releasing system based on gold nanoclusters for glucose control in type 1 diabetes." (PMID 31159842, 2019). "The hallmarks of type 1 diabetes are decreased insulin production, enhanced glucose production, and hyperglycemia, which occur due to loss and dysfunction of pancreatic β-cells." (PMID 31757001, 2019).